HLA-G (major histocompatibility complex, class I, G)
Diseases named in the same sentence as HLA-G in open-access papers (continued):
Sharing a sentence is not in itself a finding about the gene and the disease.
liver disease (4 papers, 2020 to 2023). "Outside of transplantation, HLA-G is also associated with certain liver diseases, as it has been detected in the livers of patients infected with hepatitis C virus (HCV) and shown to be associated with fibrotic lesions." (PMID 36897848, 2023). "for instance showed that HLA-G did not have a protective role after liver transplantation, but that end-stage liver disease was associated with HLA-G expression on hepatocytes." (PMID 35769475, 2022).
metastatic colorectal cancer (4 papers, 2020 to 2024). "It was shown that carriers of the HLA-G 14 bp ins allele lacked a complete first-line chemotherapy response in metastatic colorectal cancer patients." (PMID 38391781, 2024).
oral squamous cell carcinoma (4 papers, 2019 to 2024). "However, the expression of HLA-G protein was significantly downregulated in oral squamous cell carcinoma." (PMID 38427106, 2024). "The expression of HLA-G in oral squamous cell carcinoma was higher than that in normal oral mucosa, which was correlated with tumor stage and lymph node metastasis." (PMID 38427106, 2024).
ovarian tumors (4 papers, 2008 to 2020). "This phenomenon may help to maintain the transcription of HLA-G in ovarian tumors under hypoxic conditions, thus, allowing the tumor cells to evade cytotoxic T lymphocyte recognition and destruction." (PMID 28781970, 2017). "Since HRE is the binding site of a known repressor of HLA-G expression (HIF-1), we hypothesize that methylation of the region surrounding the HRE may help maintain the potential for expression of HLA-G in ovarian tumors." (PMID 18498645, 2008). "To determine if levels of HLA-G expression are significantly different between ovarian tumors and OSE cells, we determined relative expression levels (real time RT-PCR) of 3 OSE samples and tumor cells isolated by LCM from 4 malignant and 4 benign ovarian tumor samples." (PMID 18498645, 2008). "The fact that the significant differences in methylation we observed between OSE and ovarian tumor samples do not correlate with differences in HLA-G expression may serve to underlie this distinction." (PMID 18498645, 2008). "Hypomethylation of these sites in ovarian tumors may serve to potentiate HLA-G expression." (PMID 18498645, 2008). "However, preventing the binding of a potential repressor protein (HIF-1) may help maintain the transcription of HLA-G in ovarian tumors under hypoxic conditions thus allowing the tumor cells to evade cytotoxic T lymphocyte recognition and destruction." (PMID 18498645, 2008). "In addition, we measured the relative levels of HLA-G expression in 11 OSE and ovarian tumor samples from which cancer cells were isolated using laser capture microdissection (LCM)." (PMID 18498645, 2008). "Thus, the significant difference in methylation levels within the promoter region observed between OSE and the ovarian tumor samples was not correlated with differences in HLA-G expression." (PMID 18498645, 2008). "Our results indicate that alterations in methylation may be necessary but not sufficient for HLA-G expression in ovarian tumors." (PMID 18498645, 2008).
placental abruption (4 papers, 2020 to 2022). Vaginal bleeding preceding the 20th week of gestation. "However, HLA-G was found to be associated with placental abruption and with overall pregnancy complications." (PMID 34685432, 2021). "Specifically, HLA-G gene polymorphisms and decreased levels of sHLA-G have been found to be related to embryo implantation failure, recurrent spontaneous abortion, placental abruption and pre-eclampsia." (PMID 33193435, 2020). "HLA-G plasma level in women with placental abruption was significantly decreased." (PMID 33193435, 2020).
ulcerative colitis (4 papers, 2010 to 2023). An inflammatory bowel disease involving the mucosal surface of the large intestine and rectum. "Based on the conducted research, the authors postulate that the insufficient secretion of IL-10 and HLA-G may lead to the development of inflammatory changes in ulcerative colitis." (PMID 34948145, 2021). "Furthermore, HLA-G expression on the surface of epithelial intestinal cells seems to play a role in the suppression of proinflammatory cytokines in ulcerative colitis." (PMID 22654952, 2012).
uveitis (4 papers, 2019 to 2025). An inflammatory process affecting a part of or the entire uvea. "Additionally, HLA-G’s ability to inhibit vascularization and induce T regulatory function may both help maintain immune tolerance in uveitis and prevent complications associated with inflammatory neovascularization such as choroidal neovascularization, cystoid macular edema, and secondary glaucoma." (PMID 35408825, 2022). "However, research in experimental models, such as uveitis, has shown that increasing HLA-G levels can significantly improve clinical manifestations, indicating its potential as a therapeutic target." (PMID 40799641, 2025). "The therapeutic use of AAV-HLA-G may be advantageous over other gene therapy approaches due to HLA-G’s wide and diverse immunomodulatory functions, which can target the multiple immunologic and inflammatory cascades active in uveitis." (PMID 35408825, 2022). "Due to its potent activity, HLA-G may have efficacy as a therapeutic in several ocular diseases, such as corneal neovascularization, neovascular glaucoma, uveitis, diabetic retinopathy, age-related macular degeneration, and other diseases of the ocular posterior segment." (PMID 35408825, 2022).
acute lymphoblastic leukemia (3 papers, 2014 to 2023). Leukemia with an acute onset, characterized by the presence of lymphoblasts in the bone marrow and the peripheral blood. "We previously reported that highly soluble HLA-G (sHLA-G) levels in the bone marrow were associated with a high blood cell count in T-acute lymphoblastic leukemia, a marker associated with a poor prognosis." (PMID 35774498, 2022).
alcoholic cirrhosis (3 papers, 2021 to 2023). "In alcoholic cirrhosis, morphological characteristics of HLA-G+ cells correspond to mast cells, and identification of HLA-G+ cells showed that 51% were mast cells, and mast cells expressing HLA-G were located in the fibrosis region." (PMID 36176778, 2022). "We enumerated HLA-G+ cells and mast cells by the immunohistochemistry of (i) liver blocks from 41 cases of alcoholic cirrhosis, (ii) 10 of idiopathic pulmonary fibrosis (IPF), and (iii) 10 of renal fibrosis." (PMID 34830373, 2021). "More than half of all HLA-G+ cells were mast cells in fibrotic areas of alcoholic cirrhosis and IPF." (PMID 34830373, 2021). "Another relevant result is the observation of HLA-G+ cells in cell nodes, near the fibrotic regions in rare cases of alcoholic cirrhosis." (PMID 34830373, 2021). "HLA-G+ and CD117+ cells were counted over the entire surface of serial slides of 41 cases of alcoholic cirrhosis using HALO software with the appropriate algorithm following immunohistochemistry with 4H84, which recognizes HLA-G, and anti-CD117/c-kit." (PMID 34830373, 2021).
anemia (3 papers, 2013 to 2025). A reduction in the number of red blood cells, the amount of hemoglobin, and/or the volume of packed red blood cells. "Capillary blood samples were taken for anaemia determination using a haematology autoanalyzer, malaria infection status, and parasitaemia were assessed via microscopy, and HLA-G 14 bp polymorphism using PCR." (PMID 40953010, 2025). "Similarly, the HLA-G 14 bp + /- variant was associated with higher odds of anaemia among participants who received iron supplements." (PMID 40953010, 2025). "Also, the HLA-G 14 bp + /- variant was linked to a higher risk of anaemia development among participants who received iron supplements." (PMID 40953010, 2025).
atopic dermatitis (3 papers, 2016 to 2021). "HLA-G expression was also studied in patients with atopic dermatitis." (PMID 34201301, 2021). "Finally, in allergic patients with atopic dermatitis HLA-G molecules are expressed by T cells, monocytes-macrophages and Langerhans cells infiltrating the dermis." (PMID 35082780, 2021). "Finally, HLA-G molecules are expressed by T cells, monocytes-macrophages, and Langerhans cells infiltrating the dermis of atopic dermatitis patients." (PMID 27413762, 2016).
Behcet disease (3 papers, 2010 to 2021). A chronic, relapsing, multisystemic vasculitis characterized by mucocutaneous lesions, as well as articular, vascular, ocular and central nervous system manifestations. "HLA-G allelic variants inducing a significantly lower expression level of HLA-G products are genetic risk factors for Behcet's disease, a chronic multi-systemic disorder involving gastrointestinal, mucocutaneous, ocular, vascular, central nervous and articular systems." (PMID 30574154, 2018). "In patients with Behcet's disease, the frequency of haplotypes containing the HLA-G 3741_3754 14 base pair insertion and 1597*delC was found to increase, and this insertion was associated with a lower serum level of HLA-G." (PMID 20573271, 2010).
bladder transitional cell carcinoma (3 papers, 2021 to 2024). The most common morphologic subtype of urinary bladder carcinoma (over 90% of cases). "This is the case for bladder transitional cell carcinoma, which was associated with the presence of HLA-G*01:01 in a Brazilian cohort." (PMID 39408976, 2024). "The data suggested that HLA-G expression was significantly favorably associated with overall survival (OS) in bladder urothelial carcinoma (BLCA) (P=0.0029), BRCA (P=0.022), ESAD (P=0.0086), KIRC (P=2.6E-05), KIRP (P=0.012), LIHC (P=0.0019), and THCA (P=0.015)." (PMID 34276642, 2021). "Immunohistochemical analysis of 75 primary bladder transitional cell carcinoma (TCC) lesions demonstrated a HLA-G expression in 51 of 75 tumors while the normal bladder lacks HLA-G expression." (PMID 35185904, 2022).
cervical disease (3 papers, 2015 to 2018). "Our findings suggest that HLA-G-driven immune mechanisms play an important role in the progression from low-grade to high-grade lesions in cervical disease." (PMID 30619504, 2018). "Since HIV and HPV present distinct biological behavior, we further analyzed the relationship between the HLA-G 3’UTR polymorphic sites and aneuploidy, which may represent the initial step for progression towards cervical malignancy." (PMID 30278059, 2018).
chronic lymphocytic leukemia (3 papers, 2011 to 2026). "In hematological malignancies, specific genotypes, including the homozygous deletion variant, have been linked to increased levels of membrane-bound and soluble HLA-G, correlating with impaired immune surveillance and reduced survival, particularly in chronic lymphocytic leukemia." (PMID 42083155, 2026).
coronary heart disease (3 papers, 2019 to 2025). "The 14 bp INS/DEL polymorphism in the 3′UTR of HLA-G can also have an effect on the susceptibility to diabetes and coronary artery diseases (CHD), therefore suggesting a novel candidate gene." (PMID 31663031, 2019). "Hypomethylation at CpG cites within the 5’UTR of the HLA-G gene, correlates with vascular calcification scores, thereby linking epigenetic regulation of HLA-G to the severity of coronary heart disease." (PMID 41445738, 2025).
gynecological cancers (3 papers, 2022 to 2024). "Although limited publication bias proves the robustness of our analyses, this meta‐analysis is the first to investigate HLA‐G polymorphisms and sHLA‐G expression in gynecological cancers." (PMID 35759240, 2022). "We determined the association between polymorphisms in the 3′ untranslated region of HLA‐G and soluble HLA‐G (sHLA‐G) expression with gynecological cancers (GCs)." (PMID 35759240, 2022). "We identified 83 eligible studies concerning HLA‐G polymorphisms in gynecological cancers." (PMID 35759240, 2022). "HLA‐G, a potent inhibitory checkpoint of immune cell function, is highly expressed in gynecological cancers." (PMID 35759240, 2022). "Soluble HLA‐G levels were significantly higher in gynecological cancers compared with the controls (SMD = 1.434, 95% CI = 0.442–2.426, p = 0.005)." (PMID 35759240, 2022).
head and neck cancer (3 papers, 2024 to 2025). A primary or metastatic malignant neoplasm affecting the head and neck. "Increased HLA-G expression has also been associated with a risk of HPV infection, which is one of the causative agents for head and neck cancer." (PMID 38391781, 2024).
head and neck squamous cell carcinoma (3 papers, 2021 to 2024). A squamous cell carcinoma that arises from any of the following anatomic sites: lip and oral cavity, nasal cavity, paranasal sinuses, pharynx, larynx, and salivary glands. "The expression of HLA-G was found to be significantly higher in tumor lesions from patients with head and neck squamous cell carcinoma (HNSCC) and oral squamous cell carcinoma (OSCC) compared to controls." (PMID 38391781, 2024). "In head and neck squamous cell carcinoma (HNSCC) tumors, the effect of HLA-G, ILT2 and ILT4 expression on cancer development has to be explained." (PMID 38391781, 2024).
heart failure (3 papers, 2016 to 2023). Inability of the heart to pump blood at an adequate rate to meet tissue metabolic requirements. "It was reported that HLA-G is upregulated in response to rejection of organ transplantation, and heart failure (HF), suggesting a putative role to modulate the inflammatory condition." (PMID 32790754, 2020).
High Blood Pressure (3 papers, 2014 to 2017). "This could reflect the participation of HLA-G in the modification of blood pressure; however, whether this polymorphism increases the susceptibility to hypertension or is a consequence of chronic diseases requires further study." (PMID 24689061, 2014).
kidney cancer (3 papers, 2017 to 2021). Primary or metastatic malignant neoplasm involving the kidney. "The bubble chart showed the methylation level of HLA-G in kidney cancer cell lines data from the CCLE database." (PMID 34276642, 2021).
nasopharyngeal carcinoma (3 papers, 2014 to 2021). A carcinoma arising from the nasopharyngeal epithelium. "Considering the HLA-G coding segment, the +755C/A (non-synonymous Leu/Ile substitution at codon 110, which defines the HLA-G*01:04 protein group) was associated with protection against more severe nasopharyngeal carcinoma tumor stages." (PMID 25699038, 2015). "In nasopharyngeal carcinoma (NPC), HLA-G is positively correlated with CD68+ macrophages and IL-10 expression, indicating that HLA-G may regulate immune escape in NPC." (PMID 34868081, 2021).
oral carcinoma (3 papers, 2021 to 2024). "Three studies reported on the association between HLA-G expression and clinical outcome of oral carcinoma patients." (PMID 34361031, 2021). "Overall, study sample sizes should be upscaled before any definitive conclusions concerning the association between HLA-G expression and clinical outcome of oral carcinoma patients can be drawn." (PMID 34361031, 2021). "Concluding, tumour HLA-G expression does not seem to significantly associate with OS time in oral carcinoma patients." (PMID 34361031, 2021). "Among a cohort of 80 oral leukoplakias evaluated by IHC for immunomodulatory mediators, increased expression of HLA-G/E, IL10, TGFβ2/3 was noted when compared with oral carcinoma samples." (PMID 36860910, 2021).
pregnancy disorder (3 papers, 2019 to 2021). A disorder that is related to pregnancy. "In pregnancy disorders, decreased HLA-G expression in extravillous trophoblasts is linked to the incidence of pre-eclampsia." (PMID 33574829, 2020). "Research should now be focused on developing safe strategies to selectively suppress or enhance immune responses regulated by HLA-G that can be applied to women with pathological pregnancy disorders, as well as patients receiving transplants or with a life-threatening tumor." (PMID 34777357, 2021).
prostate carcinoma (3 papers, 2021 to 2024). A carcinoma that arises from epithelial cells of the prostate gland. "We found one previous study reporting the influence of HLA-G 3′UTR polymorphisms in prostate cancer susceptibility." (PMID 34697671, 2022). "This is in line with a study analyzing the potential use of HLA-G 3’UTR for prostate cancer prediction, in which the +3003C variant was suggested as a tag SNP for prostate cancer risk." (PMID 35095919, 2021).
Sepsis (3 papers, 2017 to 2025). Sepsis is defined as life-threatening organ dysfunction caused by a dysregulated host response to infection. "In addition, different human leukocyte antigen G (HLA-G) polymorphisms have been associated with distinct levels of HLA-G expression and with the development of sepsis." (PMID 37833739, 2023).
thyroid tumor (3 papers, 2020 to 2023). A benign or malignant neoplasm affecting the thyroid gland. "Besides the direct involvement of BRAFV600E in thyroid tumor initiation and dedifferentiation, previous studies have reported an association of PTC with an immunosuppressive signature at mRNA level, as evidenced by the induction of the CTLA-4, PD-L1, and HLA-G genes." (PMID 37569841, 2023). "Indeed, HLA-G expression is absent in non-pathological histologic tissue whereas HLA-G expression is determined to be present in all thyroid tumors." (PMID 32922387, 2020).